CD40 (CD40 molecule)
Diseases named in the same sentence as CD40 in open-access papers (continued):
Sharing a sentence is not in itself a finding about the gene and the disease.
melanoma (continued). "CD40 expression is not limited to cells of the hematopoietic system, and has been found detectable on a variety of human carcinomas, including bladder, breast, ovarian, lung as well as in melanoma cell lines." (PMID 16545138, 2006). "Insights from previous research suggest that targeting the CD40L-CD40 pathway could offer therapeutic benefits for a wide range of patients, given the prevalent CD40 expression in various cancers such as melanoma and carcinoma, which are vulnerable to CD40-triggered cell death." (PMID 40397730, 2025). "We therefore determined whether agonist anti-CD40 mAb (FGK45.5 or FGK) in combination with PPARγ (T0070907 or T007) or PPARδ (GSK3787 or GSK) inhibitor may achieve efficient antitumor responses in mice with established B16 melanoma (left)." (PMID 37291146, 2023). "In addition, the CD40 expression level has been shown to correlate with markers of antigen presentation and type-I T-cell responses, which are associated with a better OS in a pan-cancer study and therapeutic efficacy of ICI in several melanoma trials." (PMID 35806358, 2022). "Namely, the authors observed that CD40-deficient MDSC adoptively transferred to melanoma-burdened mice failed to induce Treg in vivo, suggesting that the CD40/CD40L axis might be crucial for MDSC-mediated inhibition of Teff as well as the expansion of Treg." (PMID 33430105, 2021). "Due to the small sample size of paired BRAF inhibitor samples from the BRAF inhibitor clinical trial, we could only identify a trend toward a correlation between CD40+ melanoma and patient survival, which warrants future trials to validate the role of CD40+ melanoma cells in treatment responses." (PMID 34092233, 2021). "To determine whether these findings regarding induction of CD40 expression observed in mouse melanoma models are recapitulated in human melanoma, we evaluated the effects of RGS on the growth of two human melanoma PDX tumors previously established and characterized in our laboratory." (PMID 34092233, 2021). "Taken together, the results suggest that our pNK cells with a high expression of CD40L and CCR5 may induce high cytotoxic effects on CD40-high cancers, such as melanoma, breast, and head and neck cancers, or CCL5-high cancers, such as ovarian, metastatic breast, cervical, and gastric cancers." (PMID 34686187, 2021). "Notably, when RGS was combined with any of these RAS pathway inhibitors, the induction of CD40 expression in melanoma cells was further increased, suggesting pathways downstream of RAS may cooperate to restrain baseline CD40 expression in melanoma cells." (PMID 34092233, 2021). "In addition, substantial CD40 expression was detected in a variety of common solid cancer types including bladder cancer (102/131, 78%), melanoma (41/71, 57.7%), breast cancer (53%), lung cancer (67/129, 51.9%), colon cancer (87/110, 79%) as well as B-lineage malignancies." (PMID 32582531, 2020). "Furthermore, the expression of CD40 has been documented in many other carcinomas, such as melanomas, hepatocellular carcinomas thyroid, bladder, colon, esophageal squamous cell, ovarian, gastric, cervical, breast and pancreatic cancer, as well as in the vast majority of hematological malignancies." (PMID 31137630, 2019). "To evaluate the therapeutic efficacy of combining agonistic anti-CD40 monoclonal antibody (anti-CD40 mAb) therapy with sunitinib treatment, we analyzed the response to combination therapy or monotherapy in two different murine subcutaneous tumor models, B16.F10 melanoma and T241 fibrosarcoma." (PMID 27385210, 2016). "CD40 mAb combined with epacadostat, an IDO1 inhibitor, reduced tumor growth in B16-F10 melanoma, accompanied by an increase in tumor-infiltrating T cells." (PMID 38539263, 2024). "The ITRGM signature includes GBP5, HLA-DPB1, XBP1, CD40, CXCL10, and TNFSF13B, each playing pivotal roles in the immune response and tumor microenvironment of melanoma." (PMID 39355255, 2024).
melanoma (continued). "Using flow cytometry, we found that CD79b+ neutrophils expressed higher levels of the antigen presentation-related proteins, namely CD40, CD80, and HLA-DR, compared to other neutrophils in melanoma subjects." (PMID 38022639, 2023). "We have previously shown that RGS induces tumor cell expression of CD40 and enhances the response to anti-PD1 in several immune-competent mouse models of melanoma." (PMID 37509357, 2023). "Combining immune checkpoint inhibitors with immune factor antagonists (CD40, CD137, CD134, CD357) has demonstrated some synergistic benefits in the treatment of advanced melanoma in clinical studies." (PMID 37215082, 2023). "Alternatively, it may be preferential to deliver anti-CD40 at a lower dose via subcutaneous injection to target specific tumor deposits, draining lymph nodes, or vaccine-specific sites, which is an approach we are currently exploring in a melanoma clinical trial at our institution." (PMID 34282297, 2022). "A clinical trial with CD40 agonists, poly-ICLC, and peptide vaccines has been initiated for melanoma patients (NCT04364230)." (PMID 35062731, 2022). "Our data show that CD40 expression is prognostic for therapeutic response to RGS, RAF inhibitor and ICB treatments in human melanoma cells." (PMID 34092233, 2021). "In mouse melanoma, tumor endothelial cells upregulate IDO1 in response to the increased secretion of interferon (IFN)γ by CD40-stimulated immunotherapy, revealing a new immunosuppressive feedback mechanism." (PMID 34136377, 2021). "After coincubation of cGAMP@dual-anti-Exos and melanoma B16F10 cells for 2 hours, the red fluorescence comes from anti-CD40 and green fluorescence comes from anti-PD-L1 which can be both observed in tumor cells." (PMID 34541546, 2021). "Herein, we evaluated the role of anti-CD40 agonistic antibody (αCD40) combined with focused ultrasound (FUS)-induced boiling histotripsy (HT) in TME activation and ICI therapy of melanoma tumors." (PMID 33391491, 2021). "Together, these data suggest that melanoma cell-intrinsic CD40 correlates with response to ICB and response to inhibitors of the RAS-mediated pathways, including RGS, in melanoma patients." (PMID 34092233, 2021). "Anti-CD40/CpG-liposomes successfully sequestered anti-CD40 and CpG in vivo, significantly inhibited tumor growth and induced a survival benefit in a B16F10 murine model of melanoma." (PMID 34683963, 2021). "At the mechanistic level, RGS monotherapy and in combination with ICB sensitizes tumors to immune activation via induced immunogenic cell death (ICD), associated with upregulation of costimulatory signals (such as CD40, CD80, and ICOS-L) on melanoma cells." (PMID 34092233, 2021). "We compared their characteristics to the melanoma TAMs, evaluating the expression of CD11b, F4/80, Ly6C, CSF1R, iNOS, CD40, CD86, MHCII, Arg1, CD163 and CD206 expression by flow cytometry." (PMID 34572807, 2021). "We next conducted 6-color (hematoxylin, CD40, CD80, CD11c, CD8 and SOX10) multiplex IHC staining on the section of tumors from melanoma patients treated with BRAF inhibitor." (PMID 34092233, 2021). "Exposure to A375 melanoma sEVs reduced the HLA-DR mRNA level to about 80% of the untreated control, while class I MHC molecules and CD40 were slightly up-regulated (<1.5-fold)." (PMID 31269655, 2019). "It upregulated major histocompatibility complex (MHC) and co-stimulators CD40 and CD86 expression, promoting melanoma cells’ antigen presenting capability." (PMID 30537988, 2018). "The combined immunotherapy potently induced M1 markers (CD40, CD80, CD86, MHC II, TNFα and IL12) in vivo and synergised with chemotherapeutic regimens potently inhibiting tumour growth in melanoma and neuroblastoma mouse models." (PMID 30577495, 2018).
melanoma (continued). "Since melanoma tumors contain antigen-presenting cells which constitutively express CD40 on their surface, we hypothesized that the activation of these APCs with the CD40 agonist ISF35 might induce tumor-specific CD8 T cell immunity and effective treatment of local and disseminated tumors." (PMID 29129918, 2017). "Trichostatin A (TSA), a pan-HDACi, in combination with valproic acid (VPA), a class I/IIa HDACi, has been reported to enhance cell surface expression of class I MHC and co-stimulatory molecules CD40 and CD86 in melanoma cells." (PMID 28572863, 2017). "In the B16.F10 melanoma model, CD86 surface expression was significantly up-regulated on cDCs in tumor draining lymph nodes in mice treated with anti-CD40 mAb in combination with sunitinib versus control." (PMID 27385210, 2016). "Toll-like receptor (TLR) signalling can cooperate with CD40 activation in this regard; for example, co-administration of CD40 and TLR9 ligands in mice elicits a more effective anti-melanoma response than either ligand alone." (PMID 19906293, 2009). "While CD40 is expressed in various cancers such as carcinomas, melanomas, and B cell lymphomas, its engagement does not uniformly lead to cancer cell death." (PMID 40397730, 2025). "Although CD40 mAbs have not achieved substantial single-agent anti-tumor activity, except for melanoma, combination with chemotherapy, radiotherapy, or immunotherapy has resulted in tumor regression in different cancer types." (PMID 39103878, 2024). "Furthermore, our findings showed that combination therapy with anti-PD-L1 antibody and TLR-7/8 agonist also required CD40 positive B cells and their chemokine CXCL13 to generate optimum anti-melanoma immunity." (PMID 35720386, 2022). "In our recent study, a remarkably digital “responder” vs “nonresponder” phenotype was observed when melanoma-bearing mice were treated with anti-CD40 and polyIC without further tumor antigen treatment." (PMID 34282297, 2022). "In our current analyses, we found that pyroptosis is significantly associated with the increased expression of multiple immune checkpoint factors in the melanoma microenvironment, such as PD-1/PD-L1, CTLA4, TIM3, LAG3, and immune activation-related molecules, including OX-40, CD40, and CD86." (PMID 36513682, 2022). "Additionally, the potential value of various new inhibitory immune checkpoints (BTLA, B7 family, IDO-1, LAG-3) and costimulatory molecules (GITR, ICOS, OX40, 4-1BB, CD40, CD27) has been confirmed for melanoma treatments." (PMID 36125617, 2022). "Importantly, a recent study from our lab demonstrated that CD40 agonist vaccination with protein can elicit both CD4+ and CD8+ T cell responses to control murine melanoma with equivalent effectiveness." (PMID 34282297, 2022). "CD40-specific antibodies with TLR agonists, compared to either agent alone, significantly boosted the magnitude of CD8+ T cell responses to peptide-based vaccination in murine melanoma models." (PMID 34282297, 2022). "Given the immune-modulatory role of CD40 to promote DC and T-cell responses, we next questioned whether expression of CD40 would correlate with response to ICB immune therapy in melanoma." (PMID 34092233, 2021). "CD40 expression on melanoma cells stimulates the formation of CD8 T cell cytokines including IL-13, IL-6, TNF-α, and granulocyte/macrophage colony-stimulating factor (GM-CSF) and impedes brain metastasis which is common among melanoma patients." (PMID 32902664, 2021). "While mTOR inhibition (PP242 and Everolimus) did not promote CD40 expression on melanoma cells, suppression of either MEK or AKT pathways, induced CD40 expression in BRAFmut YUMM3.3 cells." (PMID 34092233, 2021). "There is a wide range of CD40 expression per patient and for 3 out of 14 patients there was no detectable CD40 expression in the melanoma cells." (PMID 34092233, 2021).
melanoma (continued). "In an autochthonous mouse melanoma model that is inherently resistant to checkpoint blockade and displays low baseline levels of CD8+ T cell infiltration, the combination of anti-CD40 and CSF-1R inhibition increased the expression of TNF-α in TAMs and IFN-γ production in T cells." (PMID 33804039, 2021). "The combination of agonistic anti-CD40 with antiangiogenic antibodies targeting two pro-angiogenic factors, VEGF-A and ANG2, facilitated tumor rejection and induced immune response in murine tumor models of colon cancer and melanoma." (PMID 34209679, 2021). "By querying The Cancer Genome Atlas (TCGA, N = 480) patient datasets of melanoma samples, we found that the CD40 expression was significantly correlated with CD80 (Spearman p < 0.0001, r = 0.6456) and ICOS-L (Spearman p < 0.0001, r = 0.5209) in tumors from melanoma patients." (PMID 34092233, 2021). "The compensatory regulation of CD40 signaling mediated by the RAS/RAF/PI3K-pathway might be utilized in tumors with low intrinsic CD40 levels, such as NRASmut melanoma." (PMID 34758832, 2021). "The induction of CD40, as well as CD80 and ICOS-L, in RGS-treated melanoma tumors, may form a positive feedback loop to further sensitize tumors to RGS treatment." (PMID 34092233, 2021). "We found that CD40 expression is significantly higher in tumors from melanoma patients that respond to ICB compared to the non-responsive patients." (PMID 34092233, 2021). "We next investigated whether CD40, CD80, and ICOS-L expression correlates with the outcome and therapeutic response in melanoma patients." (PMID 34092233, 2021). "Other CD40 agonists entering the clinic including SEA-CD40, ADC-1013, and CDX-1140 are being tested for single use or in combination with either chemotherapy, vaccines, or ICBs in early clinical trials in patients with advanced melanoma." (PMID 34924562, 2021). "There is no significant alteration of CD40 expression among NRASwt/BRAFwt nevi, NRASwt/BRAFmut nevi and NRASwt/BRAFwt melanoma tissues." (PMID 34758832, 2021). "Interestingly, a recent study showed that cDC1s are also required for earlier CD4+ T cell priming, and CD40 signaling in cDC1 is critical for CD8+ T cell priming and CD4+ T cell activation against fibrosarcoma and melanoma." (PMID 34283809, 2021). "To identify the origin of these CD40+CD45− cells, we inoculated YUMM3.3 melanoma cells into mice harboring the tdTomato, which was inserted into the Gt (ROSA)26Sor locus (ROSA mice) so that every single cell originating from these mice would exhibit tdTomato+ in flow cytometric analysis." (PMID 34092233, 2021). "Moreover, a booster vaccination plus combinational treatment with CD40 stimulation and CTLA-4 inhibition resulted in complete tumor regression in a murine melanoma model." (PMID 31911758, 2020). "Here, we report that the main response to agonostic CD40 mAb therapy in murine melanoma tumor endothelial cells is not due to engagement of CD40 on endothelial cells, but secondary to IFNγ-secretion by activated cytotoxic T-cells." (PMID 32231867, 2020). "Therefore, we examined the correlation between IL-32 gene expression and the DC marker CD11c (also known as ITGAX) as well as the costimulatory molecules CD40, CD80, and CD86 in melanoma samples from The Cancer Genome Atlas (TCGA)." (PMID 32841222, 2020). "Indeed, an elevated expression of CD40 and CD86 was observed in THP-1 cells exposed to melanoma-derived sEVs." (PMID 31269655, 2019). "CD40 and CD40L are co-expressed in melanoma cells and in some carcinomas." (PMID 30441823, 2018). "Furthermore, romidepsin promotes tumour-specific T cell-mediated killing of B16/F10 murine melanoma cells and enhances the expression of class II MHC, CD40, and B7-1/2." (PMID 28572863, 2017). "As melanoma is an immunogenic tumor containing CD40-expressing myeloid cells including DCs, we tested the efficacy of ISF35 against melanoma and observed a strong efficacy against highly aggressive and established B16 melanoma." (PMID 29129918, 2017).
melanoma (continued). "However, similar to the B16.F10 melanoma model, there was a significant increase in endothelial expression of VCAM-1 for the group treated with anti-CD40 mAb in combination with sunitinib." (PMID 27385210, 2016). "In addition, we find that anti-CD40 antibodies and sunitinib therapy up-regulate ICAM-1 in B16.F10 melanoma and VCAM-1 in both models, thereby decreasing the endothelial barrier to lymphocyte recruitment." (PMID 27385210, 2016). "Pre-treatment with anti-CD40 mAb and vaccination with SIY−Kb-Ig as well as with TRP2−Kb/gp100−Db-Ig induces an endogenous SIY or tumour-antigen (TRP2/gp100) specific T cell response that significantly inhibited tumour growth in a B16-SIY melanoma mouse model." (PMID 25505552, 2014). "A melanoma cell line endogenously expressing MelanA, Mel624-38, was recognized at similar levels as the same cell line when additionally loaded with the target peptide ELA or as CD40 B cells loaded with ELA peptide." (PMID 18213373, 2008). "Furthermore, while combination anti–PD-1 and anti–CTLA-4 blockade was ineffective against weakly immunogenic melanoma tumors in mice, adding DNA-PKi (NU7441) in conjunction with STGL and anti-CD40 (NU-SL40) or knocking out DNA-PK in tumors resulted in tumor regression in 75%–100% in mice." (PMID 39436696, 2024). "DC markers HLA-DR, CD86, CD1c, ILT3 and CD40 did not significantly differ among the outcome groups in mitochondrial populations, however their expression was significantly elevated in the melanoma bad and good outcome groups as compared to HD in the glycolytic cell states." (PMID 37938561, 2023). "Given the lack of CD40 costimulatory molecule expression by melanomas, the ligation of CD86 or CD80 with T cell CD28 molecules may be even more critical." (PMID 35162988, 2022). "CD40L:CD28-transduced TCR-T58 T cells were co-cultured with the melanoma tumor cell line (SK-Mel23), which provides the activation stimulus through the TCR-peptide/MHC interaction (HLA-A2/tyrosinase, which is the ligand for TCR-T58) and expresses CD40 endogenously." (PMID 34912334, 2021). "Notably, type 2 cytokine responses (IL-5) and neutrophil responses (CXCL8/IL-8) were not altered by the changes of CD40 expression, suggesting that CD40 expression specifically correlates to the T-cell-dependent antitumor immunity in human melanoma tumors." (PMID 34092233, 2021). "However, CD40-induced DC activation was not hampered by co-treatment with sunitinib in neither the B16.F10 melanoma model nor the T241 fibrosarcoma model." (PMID 27385210, 2016). "In immunologically “hot” tumors like melanoma, where considerable immune infiltration is prevalent, the triggering of the adaptive immune responses through anti-CD40-mAb may not add any additional benefit, but it can add an advantage to “cold” tumors like TNBCs." (PMID 39941108, 2025). "Interestingly, CD40-positive but not CD40-negative B cells contributed to anti-melanoma immunity." (PMID 35720386, 2022). "However, ISF35 did not work in the absence of CD40 in host cells, suggesting that any direct killing of B16 melanoma by CD40 signaling is insufficient to induce therapeutic antitumor immunity, and instead highlighting the importance of CD40 ligation on host cells." (PMID 29129918, 2017). "In contrast to melanoma, in our orthotopic PDAC models, IL-1R1 blockade failed to enhance agonistic CD40 antibody efficacy." (PMID 40060615, 2025). "LGALS9, which has been shown to interact with CD40 on T cells thereby attenuating their expansion and effector function, was strongly expressed in CAFs from BCC and SCC but not melanoma." (PMID 39516494, 2024). "A predominant expression of IDO1 in the tumor endothelial cell fraction was also noted in HCmel12 melanomas, but the level of IDO1 and of intratumoral IFNγ were not significantly increased by anti-CD40 therapy in this model." (PMID 32231867, 2020).